IL6 (interleukin 6)
Diseases named in the same sentence as IL6 in open-access papers (continued):
Sharing a sentence is not in itself a finding about the gene and the disease.
schizophrenia (continued). "The elevation of pro-inflammatorybiomarkers such as IL-6, IL-1β, TNF-α, and CRP has beenassociated with cognitive decline, with this association being particularlypronounced in patients with deficit schizophrenia." (PMID 40926813, 2025). "The volume of cortical grey matter has also been shown to be significantly negatively correlated with IL-6 in schizophrenia." (PMID 41465427, 2025). "As in ASD, patients with schizophrenia exhibit elevated levels of proinflammatory cytokines, such as IL-1β, IL-6, and TNF-α, alongside reduced levels of anti-inflammatory cytokines, including IL-10, IL-1β, and IL-8, when compared to healthy individuals." (PMID 40276707, 2025). "Psychosis spectrum disorders such as schizophrenia and bipolar disorder are related to increased CPV, and an association has been observed between a larger CPV and higher levels of interleukin-6." (PMID 39014090, 2025). "Currently, some of the most robust cytokine findings are for IL-6, which has been described as a potential trait marker for schizophrenia in recent meta-analyses." (PMID 40358174, 2025). "Activation of STAT1 is downstream of cytokine receptors that signal from specific pro-inflammatory cytokines known to be dysregulated in schizophrenia, such as IFNγ, IL-6, IL-2, and IL-10." (PMID 40259965, 2025). "In another study of individuals with established schizophrenia, reduced CT of the bilateral Broca’s area and temporal gyrus was related to higher peripheral IL-6 levels." (PMID 39911538, 2025). "The PANSS total scores in schizophrenia displayed moderate-to-strong relations with IL-6 and TNF-α (r = 0.54 and r = 0.48), yet IL-6 and IL-1β exhibited these relations with HAM-D in patients with MDD (r = 0.46 and r = 0.41)." (PMID 40416228, 2025). "In schizophrenia, IL-6 and TNF-α were positively correlated with PANSS scores while indicating their involvement in symptom severity." (PMID 40416228, 2025). "Increased concentrations of IL-1β, IL-6, IL-10, IL-17, sIL-2R, and IL-33, but also decreased concentrations of TNF-α, were similarly associated with more severe positive symptoms of schizophrenia." (PMID 40364201, 2025). "In individuals with early and established schizophrenia combined, higher levels of plasma IL-6 were significantly related to more severe depressive symptoms (B = 0.82; 95% CI, 0.29 to 1.35; p = .002)." (PMID 39911538, 2025). "High levels of IL-6 and TNF-α are linked to mood and cognitive abnormalities, while abnormal cytokine signaling in schizophrenia is linked to poor brain connections and developmental alterations." (PMID 39861166, 2025). "Our study also identified significant associations between elevated inflammatory markers (CRP OR = 1.39; IL-6 OR = 1.22) and progression to schizophrenia." (PMID 41254065, 2025). "Cytokine levels and different inflammatory mediators, such as tumor necrosis factor-alpha (TNF-α) and interleukin-6 (IL-6), are elevated in the peripheral blood of people diagnosed with schizophrenia." (PMID 40612741, 2025). "Patients with schizophrenia showed lower levels of 5mC in the IL-6 promoter region compared with healthy controls." (PMID 38203806, 2024). "Individuals with schizophrenia exhibit elevated pro-inflammatory cytokines (e.g., IL-1β, IL-6, IL-8, and TNF-α) released by the microglia." (PMID 39839138, 2024). "A meta-analysis demonstrated high protein levels of pro-inflammatory cytokines (e.g., IL-6 and TNFα) in the peripheral blood in schizophrenia patients, where patterns of the increased cytokines are different between phases of illness." (PMID 38673876, 2024). "In line, interleukin‐6 (IL‐6) is a major proinflammatory cytokine and elevated IL‐6 levels in CSF have been reported in mood disorders, schizophrenia, and post‐traumatic stress disorder." (PMID 39317977, 2024). "Another meta-analysis revealed significant increases in protein levels of IL-6 and IL-8 in the cerebrospinal fluid of schizophrenia patients." (PMID 38673876, 2024).
schizophrenia (continued). "For example, a meta-analysis of cytokines in schizophrenia found higher levels of pro-inflammatory cytokines such as IL-6, TNF-α and sIL-2R in acute patients, and IL-6, IL-1β and sIL-2R in chronic patients than in healthy controls." (PMID 38352871, 2024). "Elevated levels of proinflammatory markers and cytokines, including interleukin 6 (IL-6), which stimulates B lymphocytes, have been observed in individuals with schizophrenia." (PMID 39816323, 2024). "Interleukin 6 (IL-6) is a cytokine involved in immune responses and is considered a potential peripheral biomarker for schizophrenia." (PMID 38203806, 2024). "A higher IL-6 concentration also predicted less improvement in depressive symptoms of schizophrenia." (PMID 39595201, 2024). "NFκB is a master immune transcription factor, which regulates inflammatory cytokines, including IL-1β, IL-6, and TNFα, and is involved in the pathogenesis of schizophrenia." (PMID 39769285, 2024). "Meta-analyses have demonstrated an increase in blood cytokine levels in patients with the first-episode psychosis and acute exacerbation of schizophrenia, including IL-6, IL-17, IL-8, IFN-γ, and TGF-β." (PMID 38807424, 2024). "IL-6 has been regarded as one of the state cytokine markers of schizophrenia, which can be increased in first-episode psychosis (FEP) and be regulated by antipsychotic treatment." (PMID 37370004, 2023). "Nevertheless, there were increasing trends in the IL-6 levels in the patients with TRS compared to the patients with treatment-responsive schizophrenia in these studies." (PMID 37370004, 2023). "In this present study, we aimed to compare the serum IL-6 levels of TRS and partially responsive schizophrenia (PRS) and explore potential sex differences in the association of TRS and IL-6 levels." (PMID 37370004, 2023). "This study not only identified a genetic correlation between schizophrenia and IS, but also suggests that IL-6, glucose metabolism, and B cell infiltration are likely to be common pathways between these diseases." (PMID 37305753, 2023). "In a study which evaluated the proinflammatory state in the first episode of schizophrenia, IL-6 was recognized as a state marker for acute exacerbations and tumor necrosis factor alpha (TNFα) as a trait marker of schizophrenia." (PMID 37032951, 2023). "A previous study suggested that proinflammatory cytokine (IL-1β, IL-6, IL-8, and TNFα) release was enhanced in whole blood from schizophrenia patients." (PMID 37210391, 2023). "Meta-analysis results showed that in patients with schizophrenia before treatment, the serum IL-6 level was higher than in healthy individuals and in patients after antipsychotic treatment." (PMID 37189796, 2023). "Of the general proinflammatory cytokines, interleukin-6 (IL-6) is most consistently elevated and has been suggested as a trait marker of schizophrenia." (PMID 37872497, 2023). "In schizophrenia patients, the serum IL-6 level is also elevated in untreated schizophrenia by approximately 1.5 standard deviation above that in healthy controls." (PMID 37168420, 2023). "GM-CSF released from many cells in response to inflammatory mediators (e.g., IL-6) was also higher in patients with schizophrenia, consistent with previous studies." (PMID 37239308, 2023). "Significantly higher levels of the pro-inflammatory cytokine IL-6 and lower levels of the anti-inflammatory IL-10 have been found in patients with schizophrenia, indicating a pro-inflammatory state." (PMID 37239308, 2023). "The effect of APs on cortisol and IL-6 levels is also a critical issue in particular since APs have been shown to induce IL-6 genes methylation, resulting in lower rates of IL-6 when prescribed in drug-naïve patients suffering from schizophrenia." (PMID 36816405, 2023). "Because NFkB and PPARs are dysregulated in schizophrenia and are associated with higher levels of neuroinflammation, the agonist of PPARs can reduce inflammatory processes, reducing TNF-α and IL-6 levels." (PMID 37371435, 2023).
schizophrenia (continued). "In previous studies on patients with schizophrenia, sex differences in IL-6 levels have been observed in patients with deficit schizophrenia and metabolic syndrom." (PMID 37370004, 2023). "BIX-01294, an inhibitor of G9a methyltransferase reduced global methylation and promoter-specific H3K9me2 levels in the peripheral blood cells of patients with schizophrenia affects the expression of some genes (IL-6, NANOG, GAD67, KLF4)." (PMID 36979236, 2023). "Atypical neuroleptics, such as risperidone, reduced serum IL-6 in schizophrenia patients, along with reducing IL-10 and TNF-α in first episode patients, which also coincided with the results of our study." (PMID 37189796, 2023). "One of the recent studies demonstrated that, in patients with schizophrenia having exposure to childhood trauma, IL-6 played a role in mediating the biological events leading to social cognitive deficits." (PMID 37627253, 2023). "Polymorphic variants of the IL1B, IL6, IL6R, IL10, IL17A, and TNFA genes have been associated with schizophrenia." (PMID 37510364, 2023). "It has been suggested that clozapine can have an effect on serum IL-6 levels in patients with schizophrenia, so we also explored the relationship between clozapine and serum IL-6 levels in the TRS group." (PMID 37370004, 2023). "Antipsychotic treatment (risperidone, olanzapine, aripiprazole) also reversed hypomethylation in the interleukin 6 (IL-6) gene promoter in schizophrenia subjects." (PMID 36979236, 2023). "A decrease in the IL-10/IL-6 ratio also confirms the activation of pro-inflammatory processes in schizophrenia." (PMID 37239308, 2023). "On the flip side, studies on peripheral blood show downregulation of tlr3 and 5 mRNA levels and upregulation of il6 and il10 mRNA levels in patients with schizophrenia, which is in contrast to evidence from brain samples." (PMID 37627253, 2023). "In contrast, whole blood stimulation studies in schizophrenia showed elevated concentrations of IL-6, TNF-α, and IL-1β post-TLR2 stimulation, and increased IL-1β alone post-TLR4 and 8 stimulation." (PMID 37627253, 2023). "A diet rich in fibers is recommended to reduce inflammatory biomarkers, such as C-reactive protein (CRP) and IL-6, which are also involved in neuroinflammatory mechanisms and schizophrenia." (PMID 36946488, 2023). "This means that these trace elements and ions protect cognitive functions from the neurotoxic effects of the IL-6/IL-23/Th17 axis, and that the lower levels in schizophrenia and MNP contribute to the overall decline in cognitive function." (PMID 36256663, 2022). "A recent study suggested that IL-6 regulates cognitive function in patients with schizophrenia via its action in the choroid plexus and BBB." (PMID 35887634, 2022). "Research has found that NE acts upon βARs on human cord dendritic cells to inhibit the LPS stimulated production of IL-23, TNF-α and IL-6, which are cytokines that have been found to be increased in schizophrenia patients." (PMID 35844244, 2022). "A meta-analysis has pointed out that IL-6 is increased in first-episode psychosis and acute relapse, and can be used as a state marker of schizophrenia." (PMID 35873262, 2022). "One type of regulatory macrophage (M2), M2b, can secrete some cytokines known to be elevated in schizophrenia including IL-1, IL-6, and TNF-a." (PMID 35844224, 2022). "In the restricted study sample of schizophrenia patients (regression #4), we found that the IL-6/IL-23/Th17 score (inversely) and magnesium and calcium (positively) explained 28.5% of the variance in the G-CoDe." (PMID 36256663, 2022). "The middle temporal gyrus overexpressed a number of genes relevant to interleukin 6 pathway proteins and neuropsychiatric disorder ontologies, including schizophrenia and autism spectrum disorder." (PMID 35353173, 2022). "Increments in cytokines such as IL-1β, TNF-α, IL-6, and IL-10 have frequently been described in schizophrenia." (PMID 36256663, 2022).
schizophrenia (continued). "In the first psychotic episode of schizophrenia, a decrease in anti-inflammatory markers, such as interleukins IL-10 and IL-4, has been observed, while pro-inflammatory factors, such as IL-6, are increased." (PMID 35269952, 2022). "In this regard, it is not possible to draw a convincing conclusion about the connection of cognitive functioning in schizophrenia with IL-6 levels on the data obtained." (PMID 35873262, 2022). "Our results are in line with meta-analytical data, which consistently shows increased levels of CRP and IL-6 in schizophrenia." (PMID 36362580, 2022). "Several cytokines such as interleukin 1β, interleukin 6, and C-reactive protein were higher in individuals with schizophrenia." (PMID 35845458, 2022). "In a later study it was found that patients with schizophrenia had significantly higher IL-6 levels compared to the control group." (PMID 35873262, 2022). "We, therefore, investigated NETs as a novel mechanism and biological target in early schizophrenia and their role together with IL-6 and childhood maltreatment in identifying cluster subgroups." (PMID 36572669, 2022). "Meanwhile, many studies have reported that IL-6 increases the prevalence of schizophrenia, and that IL-6 levels in serum of schizophrenia patients are higher than those of healthy controls." (PMID 36120298, 2022). "Higher levels of interleukin (IL)-6 and elevated neutrophil counts are consistently reported in the blood of patients with schizophrenia." (PMID 36572669, 2022). "In support of the inflammatory changes being stronger in schizophrenia, we found that IL-6 mRNA (log2FC = 0.47, FDR = 0.0021) was elevated in schizophrenia compared to controls, but was not significantly changed in either Autism or Bipolar Disorder." (PMID 35844224, 2022). "For example, the activation of TLR-3 and pro-inflammatory cytokines such as IL-6 influence the development of schizophrenia-like behavior in adult offspring." (PMID 35963926, 2022). "Several other studies have, however, found elevated IL-6 mRNA in the blood of patients compared to controls, pointing to multiple cellular contributors to increased blood IL-6 levels in schizophrenia." (PMID 35027554, 2022). "Two-step cluster analysis with the IL-6/IL-23/Th17, G-CoDe, and phenome entered as continuous variables and the diagnosis of schizophrenia as a categorical variable showed three clusters of patients with a silhouette measure of cohesion and separation of 0.66." (PMID 36256663, 2022). "We recently created a novel neuroimmunotoxic pathway index in schizophrenia, particularly deficit schizophrenia, by connecting IL-6, IL-23, and IL-17 to critical actors such as IL-21, IL-22, and TNF-α." (PMID 36429996, 2022). "Our results are in agreement with articles showing correlations between IL-6 and PANSS scores among individuals with schizophrenia, with at-risk mental states, or with another psychotic disorder." (PMID 36556337, 2022). "In contrast, relationship of serum IL-6 and cognitive functions in patients with schizophrenia was shown." (PMID 35873262, 2022). "Among pro-inflammatory cytokines, the levels of interleukin (IL)-1α, IL-6, IL-11, IL-12A, IL-15, IL-17A, and granulocyte colony-stimulating factor (G-CSF) in tears were elevated in the schizophrenia group (all P < 0.01)." (PMID 35223927, 2022). "Here we investigated NETs as a novel cellular mechanism in schizophrenia, and its role together with IL-6 and early stress in identifying cluster subgroups." (PMID 36572669, 2022). "For example, the upregulation of inflammatory cytokines such as IL-6, TNF-α, and IFN-γ yields persistent subclinical inflammation and has been linked to schizophrenia." (PMID 35711940, 2022). "It has previously been shown that there is a positive association between IL-1β, IL-6, and TNF-α and prolactin levels in patients with schizophrenia." (PMID 35958655, 2022).
schizophrenia (continued). "It is reported that schizophrenia patients with a first-episode psychosis were observed to have increased blood concentrations of IL-1β, IL-6, IL-12, IFN-ɣ, TNF-α, TGF-β and sIL-2R compared to healthy controls." (PMID 34589729, 2021). "We have not looked forward and examined the signaling pathways activated by biomarker candidates of schizophrenia, such as tumor necrosis factor-alpha, IL-1β, and IL-6." (PMID 33402704, 2021). "Increased levels of the pro-inflammatory cytokines IL-6, IL-1β, and IL-8 has been observed in CSF obtained from patients with schizophrenia." (PMID 33976392, 2021). "The mean value of hsCRP in patients with schizophrenia and controls was 2.87 ± 5.6 and 0.67 ± 0.6 mg/L respectively while the respective IL-6 values were 6.63 ± 5.6 vs 3.37 ± 4.0 pg/ml." (PMID 34465310, 2021). "In this regard, the levels of IL-6 and sIL-6R are elevated in the serum of patients with schizophrenia." (PMID 33746786, 2021). "IL-6 decreased in schizophrenia patients following treatment with a medium effect size (g: −0.48; CI −0.85 to −0.11; p = 0.011; I2 = 90%)." (PMID 33653423, 2021). "The main finding of the study is that significantly higher levels of both hsCRP and IL-6 were observed in patients with schizophrenia compared with the control group." (PMID 34465310, 2021). "A Mendelian randomization study found that blockade of IL-6 cell signaling and low CRP levels can also be associated with a higher risk for schizophrenia." (PMID 34650454, 2021). "The IL-6/IL-17 axis functions as positive feedback that should be much more thoroughly explored in schizophrenia." (PMID 35237183, 2021). "MR studies have reported potential causal associations between inflammation, particularly C-reactive protein (CRP) and interleukin-6 (IL-6), and schizophrenia." (PMID 33711016, 2021). "FKBP5 and IL6 show significant positive correlation of their expression patterns in the patients with schizophrenia in two out of the three datasets included in our meta-analysis." (PMID 33673722, 2021). "Coincidentally, another study found that subjects with schizophrenia also had significantly higher peripheral and cerebrospinal fluid IL-6 than the controls." (PMID 34744839, 2021). "In chronically ill patients, IL-6 levels were significantly increased in schizophrenia, euthymic bipolar disorder and MDD compared with controls." (PMID 34650454, 2021). "Tumor necrotic factor-α (TNF-α) and interleukin-6 (IL-6) are inflammatory markers found altered in the blood of patients with schizophrenia and mood disorders." (PMID 34603861, 2021). "The result suggests that there is a higher level of hsCRP and IL-6 in patients with schizophrenia compared to their control groups." (PMID 34465310, 2021). "After treatment of the acute illness, IL-6 levels were found to be decreased significantly in both schizophrenia and MDD." (PMID 34650454, 2021). "Forty-nine percent and 43% of patients with schizophrenia had elevated hsCRP and IL-6 values, respectively." (PMID 34465310, 2021). "Blood samples from the Zip8+/− mice, collected after LPS treatment, displayed higher levels of several cytokines, including IL-6 and IL-10, which have been shown to be elevated in schizophrenia." (PMID 33608496, 2021). "Inflammatory cytokines, especially TNF-α and IL-6, are the primary molecular targets for schizophrenia." (PMID 34393855, 2021). "Data from 62 studies, analyzed IFN-γ, IL-4, IL-2, soluble IL-2 receptor (sIL-2R), IL-1β, IL-1 receptor antagonist (IL-1RA), TNF-α, IL-6, soluble IL-6 receptor (sIL-6R), and IL-10 in schizophrenia." (PMID 33746786, 2021). "IL-1B, IL6, and IL6R genes were associated with schizophrenia in a meta-analysis and an association study." (PMID 33315097, 2021). "The pathophysiology of schizophrenia has been linked with chronic inflammation, which stimulate inflammatory markers like CRP and IL-6." (PMID 34465310, 2021).